USP39 (ubiquitin specific peptidase 39)
Diseases named in the same sentence as USP39 in open-access papers (continued):
Sharing a sentence is not in itself a finding about the gene and the disease.
glioma (continued). "Collectively, these results demonstrated that overexpressed USP39 promotes glioma cells invasion in vivo." (PMID 33811456, 2022). "In our study, not only qRT‐PCR and RIP techniques but also in vitro splicing transcription and splicing assay were established to demonstrate a novel molecular mechanism of USP39 in regulating the development of glioma." (PMID 33811456, 2022). "The human glioma cell lines U251 and U87 were selected as the targeted cells for knocking down the USP39 expression." (PMID 33811456, 2022). "The phenotypes in this study are similar to the previous study, which showed that USP39 promotes glioma progression by inducing TAZ mRNA maturation." (PMID 33811456, 2022). "Oncomine database analysis revealed that high USP39 expression was significantly correlated with poor overall survival in patients with glioma." (PMID 33811456, 2022). "Meanwhile, to further confirm the rescue effect of ADAM9 on the USP39‐regulated migration and invasion of glioma cells, we knock down the expression of ADAM9 in USP39‐overexpressed U87 cells." (PMID 33811456, 2022). "That study first revealed the functional role of USP39 in the development of glioma in vitro and in vivo." (PMID 33811456, 2022). "We further validated that the expression levels of USP39 with IHC staining in human glioma tissue microarrays (TMA) from the Department of Neurosurgery of the Second Affiliated Hospital, Zhejiang University School of Medicine (Hangzhou, China)." (PMID 33811456, 2022). "This study provides a new mechanism of effect of USP39 and reveals its pivotal involvement in the migration and invasion of human glioma." (PMID 33811456, 2022). "Results demonstrated that USP39 was significantly upregulated in all the CNS cancer types, including astrocytoma, GBM, and oligodendroglial tumor." (PMID 33811456, 2022). "In summary, our work indicated that upregulated expression of USP39 is a common event in human gliomas, and that it promotes malignant tumor properties in gliomas both in vitro and in vivo." (PMID 31332287, 2019). "Here, using expression analysis of the publicly available Oncomine database, clinical glioma patient samples, and glioma cells, we found that USP39 was overexpressed in human gliomas." (PMID 31332287, 2019). "Both efficiently knocked down USP39 mRNA by about 80% and protein expression by about 60% in all three glioma cell populations." (PMID 31332287, 2019). "In this work, we investigate the expression of USP39 in human gliomas and comprehensively study the functional role of USP39 in the development of the disease using model systems both in vitro and in vivo." (PMID 31332287, 2019). "USP39 protein levels were increased in high-grade glioma samples (WHO III–IV; n = 8) relative to low-grade glioma (WHO II; n = 4) and nonneoplastic human brain tissue samples (n = 3)." (PMID 31332287, 2019). "Knockdown of USP39 in glioma cells demonstrated that the protein promoted cell growth, invasion and migration in vitro and in a tumor model in nude mice." (PMID 31332287, 2019). "To examine the function of the protein in glioma development, we knocked down expression of USP39 in glioma cells in culture with short hairpin RNAs (shRNAs) in lentiviral constructs." (PMID 31332287, 2019). "Expression of USP39 was high in all glioma cells tested relative to NHA, so we randomly chose U87MG, A172, and P3 glioma cells for these experiments." (PMID 31332287, 2019). "USP39 mRNA and protein expression were significantly higher in the glioma cell populations than in NHA (1.9–4.2×)." (PMID 31332287, 2019). "Based on a series of luciferase reporter assays designed to probe activity in seven cancer-associated pathways, we found that events downstream of Hippo signaling were dramatically affected by USP39 levels in glioma." (PMID 31332287, 2019). "ShRNAs targeting two different coding regions of USP39 (sh-USP39-1 and sh-USP39-2) were designed and tested in the three glioma cell populations." (PMID 31332287, 2019).
glioma (continued). "We reveal that USP39 has growth-promoting properties in human gliomas, and investigation of putative oncogenic mechanisms illuminates a role in mRNA processing of TAZ, a transcriptional regulator with known oncogenic properties." (PMID 31332287, 2019). "Results demonstrated that USP39 was upregulated in many tumor types, including brain and CNS cancer." (PMID 31332287, 2019). "The expression levels of USP39 are elevated in glioma tissues and cells." (PMID 40672756, 2025). "Furthermore, the knockdown of USP39 has been shown to significantly inhibit the migration and invasion of glioma cells in vitro." (PMID 40990019, 2025). "Interestingly, USP39 acts as a pro-tumorigenic factor in gliomas that can also be regulated by other molecules." (PMID 40672756, 2025). "In addition, in vitro experiments exploring the functional role, knockdown of USP39 revealed inhibition of glioma cell growth and proliferation." (PMID 40672756, 2025). "The deubiquitinating enzyme USP39 acts directly on Cyclin B1, promoting its stabilization and expression, the transition from the G2 to M phase of the cell cycle, the proliferation of glioma cells, and tumor growth in vivo." (PMID 40990019, 2025). "Additionally, USP39 stabilizes Cyclin B1 by cleaving polyubiquitin chains, thereby promoting glioma progression." (PMID 39695108, 2024). "Therefore, to demonstrate further that ADAM9 acts as the target molecule of USP39 in the regulation of glioma cell migration and invasion, we examined the expression levels of integrin β1 in the shUSP39‐U251 cells in vitro and in vivo." (PMID 33811456, 2022). "To detect precursor and mature ADAM9 mRNA, two primer pairs were specifically designed for a region of the longest ADAM9 transcript; we found that the ratio of spliced to unspliced ADAM9 mRNA was decreased or increased in the glioma cells with USP39 siRNA or overexpressed plasmid, respectively." (PMID 33811456, 2022). "USP39 promotes the migration and invasion of glioma cells in vitro and in vivo." (PMID 33811456, 2022). "Collectively, USP39 expression positively correlates with ADAM9 expression in human glioma." (PMID 33811456, 2022). "Here, we investigated the expression and function of USP39 in patients with glioma." (PMID 33811456, 2022). "Our results suggest that USP39 could be a target for the development of novel treatment approaches for glioma." (PMID 33811456, 2022). "Results showed that USP39 promoted the migration and invasion of glioma cells by inducing the pre‐mRNA maturation of ADAM9, a metzincin cell‐surface protease involved in several biological processes such as cell migration and cell–cell interactions in several solid tumors." (PMID 33811456, 2022). "In summary, USP39 promotes human glioma migration and invasion by inducing ADAM9 mRNA maturation." (PMID 33811456, 2022). "Furthermore, six fresh human glioma tissues were used to detect the expression levels of USP39 and ADAM9 by Western blotting." (PMID 33811456, 2022). "Gene expression profiling of glioma cells transduced with short hairpin RNA (shRNA) against USP39 revealed that disintegrin and metalloproteinase domain‐containing protein 9 (ADAM9), a molecule previously related to tumor cell migration and invasion, was significantly downregulated." (PMID 33811456, 2022). "USP39 promoted the invasion of glioma cells in vivo and reduced the overall survival of the mice." (PMID 33811456, 2022). "USP39 therefore provides a novel therapeutic target for the treatment of human glioma." (PMID 31332287, 2019). "Finally, we performed IHC on primary human glioma samples (n = 33) and found that IHC scores for USP39 correlated with scores obtained for TAZ (p < 0.05)." (PMID 31332287, 2019). "USP39 may thus be a potential prognostic biomarker and therapeutic target in the treatment of glioma patients." (PMID 31332287, 2019). "In addition, USP39 enhanced the invasion ability of glioma cells in vivo." (PMID 33811456, 2022).
glioma (continued). "Thus, USP39 appears to have oncogenic properties in the development of human gliomas." (PMID 31332287, 2019). "USP39 promotes ADAM9 pre-mRNA maturation, which alters integrin β1 expression and activity and promotes migration and invasion of human glioma cells." (PMID 40990019, 2025). "The expression of TAZ proteins is regulated by USP39, which induces the maturation of TAZ mRNA and thereby exerts oncogenic properties in gliomas." (PMID 40990019, 2025). "To understand in greater depth the role of the USP39/ADAM9 axis in glioma cell migration and invasion, we detected the expression level of integrin β1, an ADAM9‐interacting protein, in U251 and U87 cells infected with USP39‐shRNA‐expressing lentiviruses." (PMID 33811456, 2022). "For instance, the ubiquitin specific protease 39 (USP39), promotes RNA processing and expression of TAZ, thus favoring glioma oncogenic features in vitro and in vivo." (PMID 31861467, 2019). "The existence of a potential link between the protein expression of USP39 and TAZ was also supported by IHC performed on sections from xenografts derived from modified U87MG and P3 cells, as well as human primary glioma samples." (PMID 31332287, 2019). "We also examined USP39 mRNA and protein levels in several cell types in culture, including P3, LN18, U87MG, U251, and A172 glioma cells, and normal human astrocytes (NHA), using qRT-PCR and western blotting." (PMID 31332287, 2019). "Immunohistochemistry revealed a positive correlation between USP39 and TAZ proteins in orthotopic xenografts derived from modified glioma cells expressing USP39 shRNAs and primary human glioma samples (p < 0.05)." (PMID 31332287, 2019). "Altogether, our data show that USP39 induces mRNA maturation and elevates the expression of ADAM9 in glioma cells and may thus be considered potential target for treating patients with glioma." (PMID 33811456, 2022). "Whereas, USP39 acts as a component of the tri‐SNP complex, the link between USP39 and overall survival in glioma was not unique." (PMID 33811456, 2022). "By analyzing the expression levels of DUBs and their correlation with GALM in gliomas, combined with in vitro experiments, four DUBs were selected, namely, USP18, TNFAIP3, USP39, and USP38." (PMID 35127693, 2021). "The similar mechanism of USP39 was also found in human glioma in which USP39 could induce ADAM9 mRNA maturation but not protein to promote glioma progression." (PMID 36582601, 2022). "However, the role of USP39 in glioma has not been well defined." (PMID 31332287, 2019). "Staining for USP39 was increased in glioma samples, and levels in high-grade gliomas (WHO III–IV; n = 28) were increased compared with low-grade gliomas (WHO II; n = 18) and nonneoplastic human brain tissue samples (n = 6)." (PMID 31332287, 2019).
osteosarcoma (9 papers, 2017 to 2025). A usually aggressive malignant bone-forming mesenchymal neoplasm, predominantly affecting adolescents and young adults. "USP39 has been found to be associated with the occurrence, progression, and poor prognosis of a variety of cancers, including melanoma, osteosarcoma, and renal carcinoma." (PMID 36046375, 2022). "USP39 expression is upregulated in osteosarcoma, and in vitro studies revealed that silencing USP39 suppressed osteosarcoma cell growth and proliferation, inducing cell cycle arrest at the G2/M phase in the majority of cells." (PMID 40672756, 2025). "Knockdown of USP39 in osteosarcoma cells resulted in reduced cell proliferation, cell cycle arrest, and induction of apoptosis." (PMID 39062505, 2024). "Bioinformatics analysis based on the publicly available Oncomine database revealed higher mRNA expression and DNA copy numbers of ubiquitin-specific peptidase 39 (USP39) in osteosarcoma cancer tissues compared to normal tissues." (PMID 39062505, 2024). "Protein imprinting analysis also indicated aberrant endogenous expression of USP39 in different osteosarcoma cells." (PMID 39062505, 2024). "Mechanistic studies revealed that USP39 inhibits the osteosarcoma cell cycle through a p21-dependent pathway and promotes osteosarcoma cell apoptosis through PARP cleavage." (PMID 39062505, 2024). "Then lentivirus-mediated short hairpin RNA (shRNA) was designed to silence USP39 in human osteosarcoma cell line U2OS, which is used to test the impact of USP39-silencing on cellular proliferation, colony formation, cell cycle distribution and apoptosis." (PMID 28403900, 2017). "It was surprising to notice a complete blocking in cancer cell colony formation, which was indicating USP39 is critical for osteosarcoma tumorigenesis." (PMID 28403900, 2017). "To better understand the role of USP39 in osteosarcoma tumorigenesis, we examined the variation tendency of cell proliferation after lentivirus infection for 5 days." (PMID 28403900, 2017). "In this present study, we employed a lentivirus-mediated RNA interference technique, a powerful tool to carry out loss-of-function assays in the investigation of cancer gene therapy, to achieve highly stable silencing of USP39 in osteosarcoma cell line U2OS." (PMID 28403900, 2017). "In this study we identified and functionally characterized the effect of USP39 gene on human osteosarcoma." (PMID 28403900, 2017). "The results uncover the critical role of USP39 in regulating cancer cell mitosis and indicate that USP39 is critical for osteosarcoma tumorigenesis." (PMID 28403900, 2017). "A further western blot analysis also demonstrated an aberrant endogenous expression of USP39 in three different osteosarcoma cells." (PMID 28403900, 2017). "USP39 (Ubiquitin precific peptidase 39) plays an important role in osteosarcoma." (PMID 36551309, 2022). "Knockdown of USP39 inhibited the growth of osteosarcoma cells and induced apoptosis in vitro." (PMID 30898977, 2019). "In summary, our findings indicate that USP39 plays an important role in the cancer cell proliferation and cell cycle regulation in osteosarcoma, and depletion of it lead to retarded cell proliferation, triggered cell cycle arrest via p21-dependent way and promoted apoptosis through PARP cleavage." (PMID 28403900, 2017).
osteosarcoma (continued). "Knockdown of endogenous USP39 expression could suppress the oncogenic properties of osteosarcoma cells and induce cell cycle arrest at G2/M phase, promote apoptosis through PARP cleavage." (PMID 28403900, 2017). "Collectively, knockdown of USP39 could markedly suppress the proliferation and colony formation ability of osteosarcoma cells." (PMID 28403900, 2017).
colon cancer (8 papers, 2021 to 2025). "Previously, USP39 depletion was found to cause a significant reduction in pre-mRNA splicing efficiency in colon cancer and glioma." (PMID 33731694, 2021). "The authors suggest that USP39 promotes colon cancer proliferation in vitro and in vivo tumorigenesis by negatively regulating p21." (PMID 41300524, 2025). "Considering the frequent presence of activating mutations in the KRAS proto-oncogene among MM and MGUS patients, with implications for disease prognosis, it is noteworthy that USP39 has been implicated in the development of KRAS-driven lung and colon cancers." (PMID 39736693, 2024). "Previous studies have reported that USP39 silencing inhibits colon cancer cell growth and metastasis, and induces apoptosis by regulating the Wnt/β-catenin signaling pathway." (PMID 38087046, 2024). "Numbers of significant differential splicing events were identified following knockdown or overexpression of USP39 in human colon cancer cells using." (PMID 36707504, 2023). "Based on our previous study of RNA sequencing, enriched GO analysis indicated that differentially expressed genes in colon cancer cells HCT116 following USP39 knockdown or overexpression were mainly associated with the function of RNA splicing." (PMID 36707504, 2023). "The expression levels of USP39 are also found increased in colon cancer tissues compared to adjacent normal tissues and correlated with poor patient overall survival." (PMID 34577547, 2021). "USP39 was also found overexpressed in colon cancer cells (LoVo, Caco, SW480 and HT29)." (PMID 34577547, 2021). "Therefore, it may be proposed that USP39 represents a potential molecular target for cisplatin therapy in the treatment of colon cancer." (PMID 40990019, 2025).
colorectal cancer (6 papers, 2019 to 2026). A primary or metastatic malignant neoplasm that affects the colon or rectum. "In addition, using Kaplan-Meier analysis, the researchers discovered that elevated USP39 expression was associated with poor overall survival in cancer patients, indicating that USP39 might contribute to the malignant progression of colorectal cancer." (PMID 40672756, 2025). "USP39 is highly overexpressed in colorectal cancer tissues and cells, while USP39 knockdown suppresses all tumor cell functions." (PMID 40672756, 2025). "USP39 knockdown induces cell apoptosis via the regulation the Wnt/β-catenin signaling pathway in colorectal cancer." (PMID 38087046, 2024). "In colorectal cancer, USP39 was reported to stabilize p21 to activate p21/CDC2/cyclin B1 pathway and promote their proliferation." (PMID 36582601, 2022). "Down-regulation of USP39 suppresses the proliferation and induces the apoptosis of human colorectal cancer cells." (PMID 30898977, 2019). "For instance, USP39 promotes colorectal cancer growth and metastasis through the Wnt/β-catenin pathway." (PMID 30898977, 2019). "In colorectal cancer, USP39 regulates apoptosis and cell proliferation via key molecular pathways." (PMID 40672756, 2025). "In this study, we examined PD-L1 expression in various types of immune cells in human colorectal cancer in connection to cancer progression-specific USPs, including USP10, USP12, USP14, USP18, USP32, USP33, and USP39." (PMID 41356798, 2026). "Although USP39 functions have been extensively studied, the role of USP36 in colorectal carcinoma remains ambiguous." (PMID 38876304, 2024).
medullary thyroid carcinoma (6 papers, 2015 to 2025). "In oral squamous cell carcinoma and medullary thyroid carcinoma, USP39 also functions as an oncogene." (PMID 33255748, 2020). "USP39 is frequently overexpressed in a range of cancers, including head and neck squamous cell carcinoma (HNSCC), oral squamous cell carcinoma (OSCC), nasopharyngeal carcinoma (NPC), medullary thyroid carcinoma (MTC), melanoma, and leukemia." (PMID 40990019, 2025).